TSNAX-DISC1 (TSNAX-DISC1 readthrough (NMD candidate))
Gene: Protein-coding gene on chromosome 1 (231,528,653 to 231,819,244, forward strand). Ensembl gene ENSG00000270106.
Genetic constraint (gnomAD): Missense variants: 167 observed, 196.19 expected, observed/expected ratio (o/e) 0.85, 90% interval 0.75 to 0.97. Synonymous variants: 74 observed, 68.59 expected, observed/expected ratio (o/e) 1.08, 90% interval 0.89 to 1.31.